TLR10 (toll like receptor 10)
Diseases named in the same sentence as TLR10 in open-access papers (continued):
Sharing a sentence is not in itself a finding about the gene and the disease.
infection (22 papers, 2011 to 2026). The state of being infected such as from the introduction of a foreign agent such as serum, vaccine, antigenic substance or organism. "Two SNP loci, 1 in TLR4 and 1 in TLR10, were associated with decreased odds of infection given increasing copies of the minor allele." (PMID 22164200, 2011). "To gain biological insights into the dynamics of human infection, we recruited a cohort of four individuals bearing the wild-type TLR10 allele (WT) and four individuals bearing a polymorphism in the TLR1/6/10 locus (TLR10 N241H (rs11096957), henceforth termed TLR10)." (PMID 31332193, 2019). "In humans, polymorphism in TLRs (TLR1, NOD2, TLR6 and TLR10) might be associated with the reduced production of cytokines after infection and finally less responsiveness of macrophages to infection." (PMID 29321921, 2018). "Our results revealed a significant parabolic increase in TLR2, TLR4, TLR7, and TLR10 expression following infection, with TLR2—the primary receptor for S. aureus recognition—showing the most pronounced response." (PMID 41305370, 2025). "Our results show that calf tracheal tissues revealed significantly elevated expression levels of TLR2, TLR4, TLR7, and TLR10, as well as MyD88 after infection with M. bovis, and initiated the innate immunity Toll-like receptor signaling pathway." (PMID 40005807, 2025). "The mRNA expression levels of TLR4–7 and TLR10 were significantly higher in KoRV-B-and KoRV-C-positive koalas than in those with endogenous infection only (KoRV-A; KJ, KY, and KYB)." (PMID 33915914, 2021). "We observed upregulation of TLR2, TLR4, and downregulation of TLR10 at the chronic stages of infection." (PMID 31555289, 2019). "This variation in the infection-induced cell states was translated to differences in infection phenotype between WT and TLR10 individuals." (PMID 31332193, 2019). "To infer variation in monocyte infection-induced states, we performed Gene Set Enrichment Analysis (GSEA) of the ‘monocytes infection-induced marker genes’ in genes that are expressed higher in WT individuals relative to TLR10 individuals." (PMID 31332193, 2019). "To further validate the link between higher NKT infection-induced state, IFNγ and infection control, we infected PBMCs from these eight individuals with Salmonella (four WT and four TLR10 individuals) and measured intracellular bacterial load by CFU." (PMID 31332193, 2019). "In line with our observation of lower NKT infection-induced state in TLR10 individuals, they had significantly higher bacterial load 8-h after infection relative to WT individuals (p = 0.03, unpaired Mann–Whitney U test)." (PMID 31332193, 2019). "Our results showed that F. hepatica infection significantly downregulated the mRNA expression of TLR1, TLR5, TLR6, TLR7 and TLR10 in PBMC at the acute stage of infection (T2)." (PMID 27661612, 2016). "Then, TLR10 involvement was analyzed by blocking TLR10 with a specific antibody (1 μg/mL for 30 min before the infection with L. monocytogenes MOI 200 along with the TLR10 antibody for 2 h), and 5-HT uptake was analyzed." (PMID 27488594, 2016). "Contrariwise, other TLRs such as TLR10 were proven to ameliorate immune responses in the setting of this infection since their activation resulted in a suppression of proinflammatory cytokines, an aspect that requires further studies, especially in pediatric patients." (PMID 35204842, 2022). "The lack of differential expression of other TLR genes in this study is in contrast to a previous study of transcriptomic response of ovine PBMC conducted by our group, where TLR1, TLR5, TLR6, TLR7 and TLR10 were downregulated in PBMC at the acute stage of infection." (PMID 34616397, 2021). "We then wanted to experimentally support cell–cell signaling between NKT cells, IFNγ secretion, and activation following infection of a monocyte subset in WT individuals as suggested by the dynamic deconvolution, and link it to overall infection outcome between WT and TLR10 individuals." (PMID 31332193, 2019).
infection (continued). "To assess whether there are differences between cell-type compositions or infection-induced states between WT and TLR10 individuals, we applied our algorithm." (PMID 31332193, 2019). "Indeed, this analysis revealed a bimodal distribution of these genes: significant enrichment of one set in genes which were expressed higher in the WT relative to TLR10, while the other set was expressed lower (8 h post-infection, p < 0.0001)." (PMID 31332193, 2019). "Thus, using our dynamic deconvolution algorithm we propose higher infection-induced state of NKT cells in WT compared to TLR10 individuals." (PMID 31332193, 2019). "Using the deconvolution algorithm, we revealed that TLR10 polymorphism is associated with attenuated infection-induced state of NKT cells and cell–cell signaling mediated by IFNγ following infection, which in turn influences infection phenotype." (PMID 31332193, 2019). "Bromocriptine-QR therapy did not, however, reduce TLR10 expression, which is an orphan receptor that is activated by pathogen-associated molecular patterns (PAMPs) and assists in the innate immune response to infection." (PMID 36012132, 2022). "Interestingly, while we could not detect any significant single gene changes between them, our algorithm found that the infection induced-state of NKT cells was significantly higher in WT vs. TLR10 individuals 8 h post-infection (p = 0.03, two sample t-test)." (PMID 31332193, 2019). "Indeed, the results showed that L. monocytogenes causes a decrease in the TLR10 mRNA level; however, the TLR10 protein level did not seem to be modified, possibly due to the short time of infection." (PMID 27488594, 2016). "However, we believe that the immunomodulatory effects of TLR10 may represent an opportunity for intervention approaches to rebalance the excessive immune response at a later stage of infection, when an excess of inflammatory cytokines can become harmful to the tissue (cytokine storm)." (PMID 39902041, 2024). "In contrast to the liver tissue, significant upregulation of TLR3, TLR4, and TLR10, but downregulation of TLR7, characterized hepatocytes derived from livers of animals with resolved AH accompanied by secondary occult infection." (PMID 30581424, 2018). "In that study, one SNP was found located within the TLR10 gene (TLR10_292 SNP), while in the current study five SNPs were found but in the TLR5 and TLR9 genes instead, also in Corriedale sheep but under natural infection." (PMID 36140716, 2022). "The functions of TLR2 on these monocyte subsets may also be dictated by the differential expression of CD14, CD16, TLR10, CD3620,55–58 and/or other receptors capable of modulating DENV infection and DENV-infection-mediated responses." (PMID 32576819, 2020). "In addition, significantly higher expression of TLR6 in CH than in the period prior to infection, TLR8 in AH than in the SLAH/SOI phase, and TLR10 in CH than in AH were apparent in both PBMC and liver biopsies." (PMID 30581424, 2018). "The results revealed distinct temporal expression profiles of Toll-like receptors (TLRs), showing that TLR2, TLR4, TLR7 and TLR10 were significantly upregulated in a parabolic pattern, with TLR2 and TLR10 peaking at 36 h while TLR4 and TLR7 reached maximum expression at 24 h post-infection." (PMID 41305370, 2025). "As a result, the expression of TLR2 and TLR10 experienced no obvious alterations during infection, and the expression of TLR5 and TLR6 increased slightly, whereas the expression of TLR4 was downregulated significantly, which were consistent with previous reports." (PMID 33414472, 2021). "The ligands of TLR10 remain unclear but it is believed that human TLR10 collaborates with TLR2 to recognize ligands from Listeria and senses influenza A virus during infection; however, TLR10 has no function in mice due to an insertion of a stop codon." (PMID 35832809, 2022).
tumor (9 papers, 2019 to 2026). "Crucially, we identified two previously under-characterized genes (RTN1 and TLR10) as potential novel drivers of tumor progression." (PMID 42186460, 2026). "The expression of TLR1, TLR3, TLR5, TLR6, TLR7, TLR8, and TLR10 show significantly decreasing trends from normal tissues to surrounding tumor tissues and to tumor tissues." (PMID 34141706, 2021). "Additionally, NF-κB activation was elevated in OSCC infiltrative zones, correlating with increased TLR9 and TLR10 expression, reinforcing its role in chronic inflammation and tumour progression." (PMID 40278081, 2025). "However, our data revealed suppression of TLR5, TLR7, TLR8 and TLR10 in PBMCs from CRC patients, suggesting a possible flip in the expression of those receptors between the tumor and periphery which warrants further investigation." (PMID 31835892, 2019).
infectious disease (8 papers, 2015 to 2026). A disorder directly resulting from the presence and activity of a microbial, viral, or parasitic agent in humans. "In humans, genetic polymorphisms in TLR10 have been associated with autoimmune and infectious diseases and cancers, including Crohn's disease, thyroid disease, complicated skin and skin structure infections, tuberculosis, nasopharyngeal cancer, and non-Hodgkin's lymphoma." (PMID 30686934, 2018). "Notably, adaptive introgression and local positive selection led to the significantly increased expression of the TLR6, TLR1, and TLR10 genes, which facilitated resistance to infectious diseases but may also be associated with increased hypersensitivity to non-pathogenic allergens." (PMID 30930906, 2019). "TLR10 is still an orphan receptor, as no ligands for it have been described, although it has been shown to have a role in some infectious diseases and to modulate responses mediated by TLR2." (PMID 32411792, 2020). "Up-regulation of TLR4 and TLR10 in NEC neonates as compared to non-NEC preterm neonates is consistent with the key role played by these bacteria sensing molecules in infectious diseases." (PMID 26801768, 2016).
cancer (7 papers, 2018 to 2025). A tumor composed of atypical neoplastic, often pleomorphic cells that invade other tissues. "However, another robust study that analyzed the expression of TLRs 1–10 in 24 urothelial cancer samples and 46 non-tumoral bladder tissue samples found the opposite, with increased expression of TLRs 2–7 and TLR10 in the cancer samples." (PMID 40778061, 2023). "Additionally, TLR6, TLR7, TLR8, TLR9, and TLR10 expression was up- or down-regulated in different cancer species." (PMID 35801728, 2022). "TLR3 and TLR10 were found to be significant in nine malignancies, while TLR4 was shown to be significant in eight cancers." (PMID 35801728, 2022). "TLR1, TLR2, TLR3, TLR4, and TLR5 expression levels were high across the six immune subtypes in the pan-cancer data; TLR6, TLR7, TLR8, and TLR10 expression levels were moderate; and TLR9, TLR12P, and TLR8-AS1 expression levels were extremely low." (PMID 35801728, 2022). "For the immune score, expression of TLRs was positively correlated with immune scores in almost all types of cancer, except TLR1 in UVM, TLR3, 4, and 5 in THYM, and TLR10 in DLBC." (PMID 35937402, 2022).
bacterial infection (1 paper, 2019). "We hypothesized that the altered immune response to bacterial ligands will manifest in differences of distinct immune cell types, which may shed light on TLR10 function during bacterial infections." (PMID 31332193, 2019).
respiratory diseases (1 paper, 2022). "The potential suppression of inflammation by regulating expression of TLR10 in lung epithelial cells may allow the development of new approaches to balance an inflammatory response and prevent extensive tissue damage in respiratory diseases." (PMID 36671404, 2022).
TLR10 also shares sentences with these, for which no sentence is quoted: atopic eczema (3 papers); Crohn disease (3); allergic rhinitis (2); hay fever (2); acute monocytic leukemia (1); acute respiratory distress syndrome (1); allergic asthma (1); Allergy (1); Arthritis (1); autoimmune thyroid disease (1); bacterial meningitis (1); bladder cancer (1); bubonic plague (1); colorectal cancer (1); extrapulmonary tuberculosis (1); hip osteoarthritis (1); Immunodeficiency (1); latent infection (1); lipodystrophy (1); lung diseases (1); melanoma (1); meningioma (1); microscopic polyangiitis (1); myxedema (1); Nasal polyposis (1); nasopharyngeal carcinoma (1); osteoarthritis (1); otitis media (1); pituitary tumor (1); pneumococcal meningitis (1).
A further 7 diseases each share a sentence with TLR10 in 1 paper.